CFAP410 (cilia and flagella associated protein 410)
Description:
Plays a role in cilia formation and/or maintenance (By similarity). Plays a role in the regulation of cell morphology and cytoskeletal organization. Involved in DNA damage repair.
Synonyms: C21orf2; LRRC76; YF5; A2; RDMS; SMDAX; YF5/A2
Tractability: Antibody: its Gene Ontology location is reachable by antibodies, with high confidence. PROTAC: ubiquitination databases record sites on it.
Gene: Protein-coding gene on chromosome 21 (44,328,944 to 44,339,402, reverse strand). Ensembl gene ENSG00000160226.
Subcellular location: Mitochondrion; Cytoplasm, cytoskeleton, cilium basal body; Cell projection, cilium, photoreceptor outer segment; Cytoplasm
Subcellular location (Human Protein Atlas): Cytosol; Golgi apparatus; Primary cilium transition zone; Basal body
Gene Ontology:
Molecular function: protein binding
Biological process: cytoskeleton organization
Cellular component: ciliary basal body; cytoplasm; cytosol; mitochondrion; photoreceptor outer segment; plasma membrane; photoreceptor connecting cilium; photoreceptor cell cilium
Genetic constraint (gnomAD): Loss-of-function variants: 17 observed, 17.53 expected, observed/expected ratio (o/e) 0.97, 90% interval 0.66 to 1.45. The upper end of that interval is the gene's LOEUF score, 1.45, which puts it in group 6 of 6, group 1 being the genes least tolerant of losing a copy. Missense variants: 396 observed, 308.31 expected, observed/expected ratio (o/e) 1.28, 90% interval 1.18 to 1.4. Synonymous variants: 170 observed, 139.06 expected, observed/expected ratio (o/e) 1.22, 90% interval 1.08 to 1.39.
Gene-disease validity (ClinGen):
ClinGen rates the evidence that CFAP410 causes each of these diseases.
ciliopathy (autosomal recessive): Definitive. A genetic disorder of the cellular cilia or the cilia anchoring structures, the basal bodies, or of ciliary function.
amyotrophic lateral sclerosis (semidominant): Limited. Amyotrophic lateral sclerosis (ALS) is a neurodegenerative disease characterized by progressive muscular paralysis reflecting degeneration of motor neurons in the primary motor cortex, corticospinal tracts, brainstem and spinal cord.
Homologues: Orthologues: chimpanzee CFAP410 (98% identical), macaque CFAP410 (93% identical), dog CFAP410 (75% identical), pig CFAP410 (74% identical), mouse Cfap410 (73% identical), guinea pig CFAP410 (71% identical), rat Cfap410 (71% identical), tropical clawed frog cfap410 (53% identical), zebrafish cfap410 (50% identical), Caenorhabditis elegans F09G8.5 (32% identical), Drosophila melanogaster CG15208 (27% identical), Drosophila melanogaster CG14995 (10% identical).
Diseases named in the same sentence as CFAP410 in open-access papers:
CFAP410 is named in the same sentence as 31 diseases in open-access papers, as found by Europe PMC text mining. Sharing a sentence is not in itself a finding about the gene and the disease. The quoted sentences say what the papers report.
ciliopathies (9 papers, 2019 to 2025). "CFAP410 has been reported to be a component of the basal body of primary cilia, and mutations in this protein have been found to be associated with ciliopathies." (PMID 40933646, 2025). "The non-syndromic cone dystrophy phenotype reported herein expands the genotypic and phenotypic spectra of CFAP410-associated ciliopathies and highlights the need for light of potential future genetic therapies." (PMID 39232248, 2024). "In conclusion, our data validate the phenotypic expansion caused by pathogenic variants in CFAP410 and expand the mutation landscape of this gene by providing novel coding and non-coding variants in this ciliopathy gene." (PMID 39516462, 2024). "Our work altogether explains how CFAP410 localizes to the basal body and why the single-residue mutation L224P causes ciliopathies." (PMID 39255848, 2024). "This study expands the current knowledge of CFAP410-associated ciliopathy by enriching its mutational landscape and supports its association with non-syndromic retinal degeneration." (PMID 38405922, 2024). "Functional genomic screens for ciliary gene identification combined with mutational screening in unsolved ciliopathy patients confirmed the essential role of the CFAP410 protein in ciliogenesis." (PMID 39516462, 2024). "Multiple single amino acid mutations in CFAP410 have been identified in patients with various ciliopathies." (PMID 39255848, 2024). "Taken together, our studies reveal that the basal body localization of CFAP410 is controlled by the CTD and provide a mechanistic explanation for how the mutation L224P in CFAP410 causes ciliopathies in humans." (PMID 39255848, 2024). "Taken together, our work provides a potential explanation how single-residue mutations in CFAP410 might cause ciliopathies." (PMID 40018707, 2025). "Besides ALS, mutations in CFAP410 have also been reported in ciliopathies such as Axial spondylometaphyseal dysplasia, Jeune syndrome and retinal dystrophy." (PMID 40933646, 2025). "Many ciliopathy cases harboring pathogenic CFAP410 variants have been described to date." (PMID 39516462, 2024). "One of these genes is CFAP410 (Cilia and Flagella Associated Protein 410), (previously known as C21orf2), which maps to chromosome 21q22.3 where pathogenic variants have most frequently been reported in association with rare syndromic ciliopathies involving the skeletal system." (PMID 39232248, 2024). "CFAP410 is a ciliary protein localized to the base of cilia in human cells and involved in ciliopathies characterized with retinal and skeletal impairment." (PMID 40018707, 2025). "These disruptions likely drive the pathogenesis of CFAP410-related ciliopathies." (PMID 40018707, 2025). "Although the presence of CFAP410 has not been confirmed in the cilia of other organs, it may affect skeletal development based on the clinical presentation of some patients with syndromic ciliopathies." (PMID 37901396, 2023).
Jeune syndrome (6 papers, 2016 to 2025). Jeune syndrome, also called asphyxiating thoracic dystrophy, is a short-rib dysplasia characterized by a narrow thorax, short limbs and radiological skeletal abnormalities including "trident" aspect of the acetabula and metaphyseal changes. "In this retrospective study, we describe sixteen families with early-onset non-syndromic retinal degenerations in which affected probands carried rare bi-allelic variants in CFAP410, a ciliary gene previously associated with recessive Jeune syndrome." (PMID 39516462, 2024). "In particular, CFAP410 is associated with Jeune Asphyxiating Thoracic Dystrophy (JATD) and Axial Spondylometaphyseal Dysplasia (axial SMD)." (PMID 39232248, 2024).
retinal degeneration (6 papers, 2016 to 2024). Degeneration of the retina. "In this retrospective study, we describe sixteen probands with retinal degeneration associated with rare bi-allelic variants in CFAP410, a gene initially associated with recessive skeletal ciliopathies like JS and SMDAX." (PMID 39516462, 2024). "Variants in CFAP410 have been associated with both syndromic (i.e., skeletal ciliopathies) and non-syndromic forms of retinal degeneration." (PMID 39516462, 2024). "Pathogenic or likely pathogenic variants were identified predominantly in genes already known to cause retinal degenerations (with a significant number of ABCA4 variants), although variants in genes newly identified as involved in retinal disorders were also uncovered (such as CFAP410 and GUCA1A)." (PMID 39202371, 2024). "A review of 95 previously published and our bi-allelic CFAP410 cases did not reveal a clear genotype-phenotype corrlelation and even suggested that a non-syndromic retinal degeneration is likely more common than the syndromic IRD/skeletal dysplasia in patients affected by variants in this gene." (PMID 39516462, 2024).
amyotrophic lateral sclerosis (5 papers, 2022 to 2025). "CFAP410 is also one of the genes implicated in amyotrophic lateral sclerosis (ALS), a fatal progressive neurodegenerative disease caused by the loss of motor neurons." (PMID 39255848, 2024). "In ophthalmology, pathogenic variants in CFAP410 have been described in association with cone rod dystrophy, retinitis pigmentosa, with or without macular staphyloma, or with systemic abnormalities such as skeletal dysplasia and amyotrophic lateral sclerosis." (PMID 39232248, 2024). "Mutations in CFAP410, a basal body protein known to be required for the formation of primary cilia, have been identified as risk modifiers in amyotrophic lateral sclerosis (ALS), a devastating late onset neurodegenerative disorder with poor prognosis." (PMID 40933646, 2025).
cone-rod dystrophy (4 papers, 2016 to 2024). Inherited retinal dystrophies that belong to the group of pigmentary retinopathies. "CFAP410 pathogenic variants Y107H and P116L were associated with isolated cone-rod dystrophy with macular staphyloma." (PMID 37901396, 2023). "CFAP410 pathogenic variants were identified in a cone-rod dystrophy with macular staphyloma patient." (PMID 37901396, 2023). "Cone-rod dystrophy (CORD) caused by pathogenic variants in CFAP410 is a very rare disease." (PMID 37901396, 2023).
Down syndrome (3 papers, 2015 to 2024). "Given its mapping position on chromosome 21, CFAP410 was initially thought to play a role in the pathogenesis of several genetic diseases including Trisomy 21 (Down syndrome), but none of these associations have been confirmed." (PMID 39516462, 2024).
retinal ciliopathy (3 papers, 2017 to 2025). "Previous studies have shown that CFAP410 is a component of a retinal ciliopathy-associated protein complex containing both NEK1 and SPATA7." (PMID 40018707, 2025). "Other studies also showed that CFAP410 is a component of a retinal ciliopathy-associated protein complex containing both NEK1 and SPATA7." (PMID 39255848, 2024). "Previous immunofluorescence studies showed that CFAP410 co-localizes with both the serine/threonine kinase NEK1 and a retinal ciliopathy protein called SPATA7 at the basal body in hTERT-RPE1 cells." (PMID 39255848, 2024).
retinitis pigmentosa (3 papers, 2023 to 2024). Retinitis pigmentosa (RP) is an inherited retinal dystrophy leading to progressive loss of the photoreceptors and retinal pigment epithelium and resulting in blindness usually after several decades. "Previous studies reported that variants in CFAP410/C21orf2 can cause retinitis pigmentosa and cone–rod dystrophy." (PMID 36833373, 2023).
Retinal dystrophy (2 papers, 2014 to 2024). Retinal dystrophy is an abnormality of the retina associated with a hereditary process. "To date, 24 CFAP410 variants have been reported in the literature in association with retinal dystrophy." (PMID 39232248, 2024). "A gene therapy for CFAP410-related retinal dystrophy would be a good candidate, since the cDNA size of 1.1kb is well within the packaging capacity of the adeno-associated viral vector—the most established vector for retinal gene supplementation." (PMID 39232248, 2024). "Currently, there is no treatment for CFAP410-related retinal dystrophy." (PMID 39232248, 2024).
cone-only dystrophy (1 paper, 2024). "Herein, we report a novel variant in CFAP410, a homozygous in-frame deletion at c.335_346, associated with isolated cone dystrophy but with no systemic features, potentially expanding the genotypic and phenotypic heterogeneity of this rare ciliary gene." (PMID 39232248, 2024). "In conclusion, we report a novel homozygous in-frame deletion in the CFAP410 gene with a cone-only dystrophy phenotype without systemic features." (PMID 39232248, 2024).
embryonal carcinoma (1 paper, 2025). A non-seminomatous malignant germ cell tumor characterized by the presence of large germ cells with abundant cytoplasm resembling epithelial cells, geographic necrosis, high mitotic activity, and pseudoglandular and pseudopapillary structures formation. "To ensure the most relevant transcript was tagged with the HA epitope, we first studied the expression of the different Cfap410 transcripts in a developmental series of mouse brain tissue and in motor neurons differentiated in vitro from P19 embryonal carcinoma cells." (PMID 40933646, 2025).
spondylometaphyseal dysplasia (1 paper, 2024). Spondylometaphyseal dysplasias are a heterogeneous group of disorders associated with walking and growth disturbances that become evident during the second year of life. "One of the mutations, L224P, is located in the C-terminal domain (CTD) of human CFAP410 and causes severe spondylometaphyseal dysplasia, axial (SMDAX)." (PMID 39255848, 2024).
CFAP410 also shares sentences with these, for which no sentence is quoted: axial spondylometaphyseal dysplasia (3 papers); cancer (2); retinal disorder (2); skeletal dysplasia (2); bacterial infection (1); CADASIL (1); cognitive decline (1); frontotemporal dementia (1); hepatic carcinoma (1); hepatic disease (1); lactic acidosis (1); MELAS (1); metabolic disease (1); migraine (1); Mitochondrial encephalopathy (1); prostate carcinoma (1); renal cell carcinoma (1); Spastic paraplegia (1); viral infections (1).